EPO (erythropoietin)
Diseases named in the same sentence as EPO in open-access papers (continued):
Sharing a sentence is not in itself a finding about the gene and the disease.
anemia (continued). "Anemia is a prevalent complication in patients with CRF and is mainly mediated by increased toxicity, inadequate erythropoietin (EPO) production, inflammation, nutritional deficiencies, and oxidative stress." (PMID 40525868, 2025). "However, since interventions such as EPO and vitamin B12 supplementation were administered predominantly to patients with the most severe anemia and were associated with lower preoperative Hb levels in our analysis, these findings may be subject to a selection bias." (PMID 40524687, 2025). "Hemodialysis patients with advanced CKD are particularly vulnerable to SARS-CoV-2, where inflammation-induced EPO resistance complicates anemia treatment." (PMID 41012526, 2025). "Renal dysfunction exacerbates anemia via erythropoietin suppression, inflammation-induced hyporesponsiveness to erythropoiesis-stimulating agents, and iron deficiency." (PMID 41348379, 2025). "He had a single dose of an iron infusion and erythropoietin 10 weeks later from anemia due to chronic kidney disease." (PMID 40565892, 2025). "​​Regarding the regulation of vascular factors, HIF bounds to EPO 5’ hypoxic response element, and EPO gene transcription increases under the condition of anemia or hypoxia." (PMID 41164084, 2025). "Insufficient erythropoietin (EPO) production in injured kidneys leads to anemia and further exacerbates kidney damage." (PMID 41179707, 2025). "This study highlights a close relationship between infection and resistant anemia, as evidenced by the need to increase the erythropoietin dose in patients with previous infection, even months after diagnosis." (PMID 40126283, 2025). "No patient was in receipt of anabolic steroids, of recombinant growth hormone, although patients were prescribed erythropoietin‐stimulating agents to manage anaemia secondary to ESKD." (PMID 39687979, 2025). "There is ongoing debate regarding the optimal management of anemia in post-transplant patients, particularly surrounding the use of erythropoietin (EPO) and newer hypoxia-inducible factor prolyl-hydroxylase inhibitors (HIF-PHIs)." (PMID 41458512, 2025). "Erythropoiesis is stimulated by the hormone erythropoietin, which is produced in the kidneys in response to hypoxia or anemia." (PMID 40872496, 2025). "For example, erythropoietin for chemotherapy‐induced anaemia modestly improved QOL and reduced transfusion needs, but it increases costs substantially (£1829.77 per patient), and a lack of evidence on survival benefits limits its cost‐effectiveness assessment." (PMID 40873470, 2025). "The causes of anemia in CKD are multifactorial, including reduced erythropoietin (EPO) production, shortened red blood cell (RBC) lifespan, chronic inflammation, and disordered iron homeostasis." (PMID 41282024, 2025). "Although erythropoiesis is enhanced, anemia likely continues due to elevated erythropoietin levels, which paradoxically heighten the vulnerability of RBCs to eryptosis." (PMID 40592821, 2025). "Erythropoietin replacement therapy is the first-line treatment; however, anemia appears less frequent and less severe in PD patients compared with HD patients, with correspondingly lower use of erythropoietin-stimulating agents (71.4% vs. 86.9%)." (PMID 41157262, 2025). "Reduced erythropoietin production, impaired iron utilization, and inflammation contribute to anaemia in these patients." (PMID 39901231, 2025). "Looking at the recruitment of renal EPO cells resulting from hypoxaemic stimuli like anaemia, low tissue oxygenation or carbon monoxide exposure, a distinct pattern can be observed depending on the strength of the hypoxaemic stimuli." (PMID 40853869, 2025). "Anemia regressed following therapy with erythropoietin (EPREX®) in three infants treated with foscarnet but required transient suspension of antiviral therapy in the fourth infant who was affected by β-microcythemia." (PMID 40431731, 2025).
anemia (continued). "The patient gradually improved during the following days and was discharged on day 9 after symptom onset, with full recovery, even though anaemia was recorded because of ribavirin use, which was treated successfully with subcutaneous erythropoietin." (PMID 41414932, 2025). "This response is likely driven by increased erythropoietin (EPO) secretion in response to 5‐FU‐induced anemia." (PMID 40923227, 2025). "Of patients who developed anemia, 5 (11.4%) received erythropoietin-stimulating agents (ESAs) only, 3 (6.8%) received blood transfusions only, and one (2.3%) received both ESA and a blood transfusion." (PMID 40920370, 2025). "These consistent findings across diverse regions reinforce the central pathophysiological role of erythropoietin deficiency and reduced marrow responsiveness in CKD-related anemia." (PMID 41216054, 2025). "This characteristic overcomes the limitation of the traditional system in requiring high concentrations of EPO, and holds translational potential for treating EPO-resistant anemia." (PMID 40868725, 2025). "Mild anemia was also documented in this patient (30%, normal range: 36%–60%) and is due to decreased erythropoiesis and lower erythropoietin levels." (PMID 41477561, 2025). "In the current study, the most commonly used intervention for anemia management was blood transfusion, administered in 73 out of 172 patients (33.9%), followed by iron therapy in fourteen patients and erythropoietin in twenty patients." (PMID 40765547, 2025). "Anemia affects nearly all individuals with ESRF, with the most common cause being decreased synthesis of erythropoietin (EPO)." (PMID 40278557, 2025). "Anemia of CKD is common and multifactorial in origin, with its primary causes including decreased renal production of EPO, altered iron metabolism, inflammatory responses, and factors affecting red blood cell survival." (PMID 41179057, 2025). "In this way, gliflozins help to treat anemia in CKD directly by removing EPO-inhibiting factors (proinflammatory substances) and indirectly by stimulating EPO production through HIF-2α and SIRT-1, as well as their impact on iron store mobilization." (PMID 40725186, 2025). "Erythropoietin (EPO) is one of the key endocrine factors produced by the kidney, and kidney disease patients frequently experience anemia due to impaired EPO production." (PMID 40221815, 2025). "Anemia in patients with CKD is of multifactorial origin; however, the most studied cause is the relative deficiency in erythropoietin (EPO) secretion." (PMID 40244253, 2025). "Patients with CKD stage 5 were identified based on prescription refill records for EPO, which are indicated for anemia and reimbursed for those with an eGFR less than 15 mL/min/1.73 m2." (PMID 40611400, 2025). "AI-powered predictive models can analyze patient data (e.g., hemoglobin levels, iron status, EPO levels) to diagnose anemia and predict disease progression." (PMID 40126293, 2025). "CKD anemia is mainly due to decreased production of erythropoietin by the kidneys, leading to impaired erythropoiesis, as well as shortened erythrocyte survival." (PMID 40126293, 2025). "One hundred and thirty-seven patients (63.4%) received an erythropoietin-stimulating agent (ESA) to treat anaemia." (PMID 39941428, 2025). "Inflammatory cytokines in TB inhibit erythropoietin response and iron utilization, leading to microcytic anemia." (PMID 41204497, 2025). "With anemia or hypoxia, erythropoietin levels rise sharply, stimulating mediators like ERFE, growth differentiation factor 15, and platelet-derived growth factor-BB to suppress hepcidin and increase iron availability." (PMID 40872496, 2025). "In addition, we found no significant changes in MCV, MCHC, and MCH, indicating that Cd may cause normocytic normochromic anemia even after acute exposure, thought to be caused by a defect in the synthesis of erythropoietin, as Cd directly causes bone marrow mesenchymal stem cell (BMSC) apoptosis." (PMID 39861156, 2025).
anemia (continued). "These mediators are predicted to play a role in the suppression of erythropoietin, thus contributing to anemia." (PMID 40757104, 2025). "Orally administered prolyl hydroxylase inhibitors are also effective for treating anemia and more convenient for outpatient treatment, but they have not demonstrated improved cardiovascular risks compared with erythropoietin and i.v. iron." (PMID 40773297, 2025). "Inhibition of FGF23 signaling in a mouse model of renal failure improved anemia by increasing erythropoietin levels, red blood cell counts, and bone marrow progenitors." (PMID 41157262, 2025). "Apart from these, anemia is a common presentation in dogs with CKD, and the hampered reduction of erythropoietin by the diseased kidneys is its major cause." (PMID 39328443, 2024). "EPO is crucial in regulating the late stages of erythropoiesis, and EPO and EPO derivatives are widely used to treat different types of anemia." (PMID 39474425, 2024). "Considering factors like drug costs, administration frequency, and healthcare utilization, a comprehensive cost-effectiveness analysis supports DPO's clinical, social, and financial advantages over EPO in CKD anemia management." (PMID 38313992, 2024). "In response to malaria induced anemia, erythropoietin levels are found to be higher in malaria patients, which in turn promotes erythrocyte formation and stimulates erythroferrone (negative regulator of hepcidin) production." (PMID 39492784, 2024). "From the percentage distribution of the total annual cost of medication by drug category, it is evident that erythropoietin administered for the treatment of anemia is the one that contributes the most to the cost of medication for all three methods." (PMID 39451489, 2024). "Anti-EPO antibodies are generated in some CKD patients after treatment with ESA and it is related with EPO resistance, resulting in worsening of the anemia." (PMID 39502472, 2024). "These mediators contribute to anemia through mechanisms like dyserythropoiesis, inadequate erythropoietin response, and disrupted iron homeostasis." (PMID 39649896, 2024). "To better understand the tissue (kidney and spleen) iron overload and presence of anemia in mice fed 1.65% Pi diet despite increased EPO secretion, we assessed the expression of heme oxygenase-1 (Hmox-1), an essential enzyme for iron recycling." (PMID 39666728, 2024). "Hepcidin obstructs intestinal iron absorption and causes iron retention in reticuloendothelial cells, resulting in restricted iron availability for erythropoiesis, shortened erythrocyte lifespan, and suppressed erythropoietin response to anemia." (PMID 38675885, 2024). "Some gut-derived uremic toxins favor anemia by reducing EPO synthesis and the erythropoietic response by inhibiting HIF activation and enhancing eryptosis (the premature stress-induced programed death of red blood cells)." (PMID 39591250, 2024). "It is also worth noting that anemia of prematurity is characterized by reduced erythropoietin production." (PMID 39456997, 2024). "In conclusion, this review provides compelling evidence of the advantages of DPO over conventional recombinant human EPO for managing anemia in CKD patients, both in the predialysis and dialysis-dependent CKD patients." (PMID 38313992, 2024). "Using erythropoietin to treat anemia in ESRD patients can reduce bleeding complications, whereas it can also increase the risk of ACS by increasing blood viscosity." (PMID 39201390, 2024). "The development of anemia in ESRD patients is influenced by various factors, such as low levels of endogenous erythropoietin (EPO), iron deficiency, chronic inflammation, inadequate nutrient intake, and shortened red blood cell lifespan (RBCLS), among others." (PMID 39685563, 2024). "Multiple factors can lead to CKD anemia, such as reduced EPO production, EPO resistance, a low erythrocyte life span, and absolute or functional iron deficiency." (PMID 39450175, 2024).
anemia (continued). "Regarding to anemia rectification, blood transfusion, erythropoietin-stimulating agents (ESAs) and iron are three main treatment modalities." (PMID 38847977, 2024). "In CKD, a critical balance between oxygen supply and demand around EPO-producing cells profoundly influences anemia development." (PMID 38612557, 2024). "Multiple factors contribute to the exacerbation of anemia in CKD, with the principal factor being linked to erythropoietin (EPO) deficiency." (PMID 39911241, 2024). "Supportive treatments, including erythropoietin-stimulating agents and androgens, help manage anemia, while hydroxyurea and interferons can also be used to control blood counts and disease progression." (PMID 39104967, 2024). "Recombinant human erythropoietin (EPO) is a biopharmaceutical frequently used in the treatment of anemia." (PMID 38254725, 2024). "Hypoxia caused by anemia triggers the production of inflammatory mediators and vasoproliferative factors like VEGF and erythropoietin." (PMID 38800491, 2024). "Considering the effect of citrate on anemia, stability of plasma hemoglobin and a decrease in the erythropoietin resistance index were found in a recent report." (PMID 38189095, 2024). "Long-term use of imatinib can lead to reversible but progressive decline in eGFR.Decline in eGFR was correlated with anemia at 5 years due to lower EPO production." (PMID 39796721, 2024). "Explored the role of erythropoietin in managing anaemia, particularly in patients with kidney disease." (PMID 39184703, 2024). "With regard to the connection between hypocarnitinemia and anemia, it has been reported that carnitine deficiency is one of the factors involved in the development of erythropoietin-resistant anemia in patients undergoing dialysis." (PMID 38982532, 2024). "Altogether, the inhibition of erythropoiesis by inflammatory markers, shortened half-life of erythrocytes and decreased biological activity of erythropoietin induce the development of anemia." (PMID 39633899, 2024). "Hormones and related therapeutic agents such as insulin, erythropoietin, and folic acid are crucial for metabolic regulation and anemia, respectively." (PMID 39252278, 2024). "In patients with tumors, the use of erythropoietin and other treatments for anemia should take into account the potential risks of tumor recurrence and accelerated progression." (PMID 39221033, 2024). "In the context of bilateral nephrectomy, rosuvastatin acts on these hypoxia-inducible factors across various organs and tissues, offering a strategic approach to anemia management by promoting erythropoietin synthesis outside the kidneys." (PMID 39221033, 2024). "This suggests that acute anemia induction triggers alterations in cellular characteristics that cannot be overcome through EPO signaling." (PMID 39284836, 2024). "EPO therapy aims to alleviate anemia by stimulating erythropoiesis, thereby improving tissue oxygenation and mitigating renal hypoxia." (PMID 39200211, 2024). "By recognizing the role of EPO and the kidneys in the dеvеlopmеnt of anemia in CKD patiеnts, healthcare providers can better understand this complication and improve patient outcomes." (PMID 39763572, 2024). "Concerns about erythropoietin (EPO) therapy for anemia in patients with end-stage renal disease (ESRD) contributing to potential bone loss and increased fracture risks are growing." (PMID 39835325, 2024). "Indicators such as methemoglobin and erythropoietin can serve as markers of anemia-induced tissue hypoxia." (PMID 38395758, 2024). "Recombinant human erythropoietin (rhuEPO) is thought to be an effective method for treating anemia in cancer patients who undergo chemotherapy." (PMID 38983914, 2024). "Chronic kidney disease can result in reduced erythropoietin production by the kidneys, leading to anemia due to inadequate stimulation of red blood cell production in the bone marrow." (PMID 38172731, 2024).
anemia (continued). "The aetiology of anaemia in cirrhosis is multifaceted, encompassing chronic inflammation, diminished erythropoietin (EPO) levels, variceal haemorrhage, hypersplenism, medication-related adverse effects, and malnutrition." (PMID 39184703, 2024). "It is well reported that levels of C-Alb or HCit differ significantly between individuals who experience meaningful clinical outcomes and those who do not (e.g., mortality, CKD progression, cardiovascular events, even anemia and erythropoietin resistance)." (PMID 38816682, 2024). "Chronic red blood cell (RBC) transfusions and/or erythropoietin (EPO)‐stimulating agents (ESAs; e.g., epoetin‐alfa or ‐beta) are often administered to correct the underlying anemia and to symptomatically manage MDS." (PMID 38434962, 2024). "Therefore, whereas iron deficiency, increased erythropoietin, and anemia may contribute to higher FGF23 levels (with total FGF23 increased more so than intact FGF23), elevated FGF23, in turn, may contribute to decreased erythropoietin and impaired erythropoiesis." (PMID 37752381, 2024). "This is mainly because with aging there seems to be a progressive resistance of bone marrow erythroid progenitors to erythropoietin, and a chronic subclinical pro-inflammatory state, resulting in anemia." (PMID 39633899, 2024). "The relationship between the impaired response of hematopoietic stem cells to EPO and the development of anemia was observed in elderly patients." (PMID 38610814, 2024). "In the presence of CRF, erythropoietin production is impaired, leading to a primary hematologic manifestation characterized by severe hypoproliferative anemia." (PMID 39460859, 2024). "There was a significant decrease in anemia prevalence and a considerable increase in erythropoietin levels after 18 weeks." (PMID 39280374, 2024). "Currently, several clinical trials are ongoing which aim to explore the treatment of anemia in patients with chronic kidney disease and cancer patients receiving chemotherapy using Peginesatide, a functional analog of erythropoietin." (PMID 38731114, 2024). "Kidney injury leads to decreased EPO levels, resulting in anemia, and continued ischemia worsens kidney function." (PMID 39724079, 2024). "In agreement with our results, EPO has previously been found to be increased in patients with obesity and anaemia, in subjects with metabolic syndrome and in individuals with abdominal obesity component." (PMID 38696124, 2024). "The identification of the hormone erythropoietin (EPO), which regulates red blood cell production, and its development into a pharmaceutical-grade product to treat anemia has been not only a herculean task but it has also been the first of its kind." (PMID 38672425, 2024). "Apart from these factors, those suffering from diabetic nephropathy (a common renal complication affecting people with DM) exhibit reduced production of erythropoietin, a hormone required for red cell synthesis, thereby aggravating further the anemia." (PMID 39634981, 2024). "Diminished levels of EPO can precipitate anaemia, characterized by either a diminished count of red blood cells or impaired red blood cell functionality." (PMID 39184703, 2024). "The synthesis of hepcidin is regulated by multifactorial influences, including anemia, systemic inflammation, and EPO." (PMID 39597967, 2024). "Decreased peritubular cell function leads to reduced circulating erythropoietin levels, exacerbating anemia." (PMID 39621534, 2024). "Most of the literature has focused on chronic disease-related anemia, particularly involving the hepcidin‐ferroportin axis and the cytokine-mediated development of erythropoietin resistance." (PMID 39575004, 2024). "Renal injury can reduce endogenous erythropoietin secretion, leading to decreased red blood cell lifespan and impaired bone marrow hematopoietic function, ultimately contributing to anemia." (PMID 39621534, 2024).